IL10 (interleukin 10)
Diseases named in the same sentence as IL10 in open-access papers (continued):
Sharing a sentence is not in itself a finding about the gene and the disease.
tumor (continued). "The IL-10 signaling pathway is presumed to play a role in the development of immunosuppressive malignant ascites within the tumor microenvironment." (PMID 38279997, 2024). "In the tumor tissue of the TH animals, high expression of Nfkb, Il1b, and Il6 was observed, accompanied by high Tgfb and Il10 expression in the peritumoral area." (PMID 39063041, 2024). "This suggests that both IL-10 and Cxcl2 mediate, at least in part, Egfl6-dependent tumor immunosuppression." (PMID 39312740, 2024). "In the present study we extended our examination to include the serum of tumor patients and healthy controls assessing levels of IgG4 and IL-10." (PMID 39896813, 2024). "Key cytokines such as TNF, IL-1, IL-6, IL-12, IL-18 (stimulatory), and TGF-β, IL-4, and IL-10 (inhibitory) mediate interactions between these cells, creating a network that facilitates tumor growth and immune evasion." (PMID 39449800, 2024). "Since the immunosuppressive cytokine IL-10-expressing oVV was reported to have a prolonged viral persistence, we measured IL-10 mRNA levels in the tumor nodules." (PMID 38473379, 2024). "The inflammatory milieu within the TME, augmented by the exosomal secretion of transforming growth factor beta (TGF-β), interleukin-4 (IL-4), and interleukin-10 (IL-10), modulates the local immune response to favor tumor progression." (PMID 39766226, 2024). "IL-10 enhances tumor growth and metastasis by upregulating CIP2A expression via the PI3K signaling pathway." (PMID 38273373, 2024). "The anti-tumor effect of IL-10 has been demonstrated in various tumor models through the activation of T cells, partially demonstrating the anti-tumor role of IL1B+ TAMs." (PMID 39232806, 2024). "In certain contexts, IL-10 can inhibit macrophage activity and promote regulatory T-cell function, potentially aiding tumor escape from immune surveillance 67,68." (PMID 39132165, 2024). "For example, we reported that blocking β-catenin or its downstream IL-10 during the T cell priming phase led to improved anti-tumor CD8 T cell responses by DC vaccines, and recent studies found that blocking β-catenin synergized with anti-PD-1 immunotherapy." (PMID 38793711, 2024). "Such macrophages express high levels of Arg-1, TGF-β, and IL-10, which play an anti-inflammatory role and promote tumor cell proliferation, metastasis, angiogenesis and intravasation." (PMID 38970071, 2024). "M2 polarization of macrophages promotes the secretion of IL-10, which ultimately leads to tumor malignancy and metastasis." (PMID 38521953, 2024). "Tumor-derived miR-6794-5p induced tumor malignancy by activating M2 macrophages in the tumor microenvironment and by inducing Interleukin 10 (IL-10) expression." (PMID 38521953, 2024). "The study results suggest preferential tumor bias towards expansion of myeloid-lymphatic cells while underscoring the role of IL-10 in early BM production of multipotent progenitors that give rise to both hematopoietic and endothelial lineages." (PMID 38640116, 2024). "In contrast, M2 macrophages are polarized by IL-4 and secrete anti-inflammatory cytokines, such as IL-10, promoting tumor progression." (PMID 39795180, 2024). "Conversely, M2 macrophages support tumor growth and metastasis by producing anti‐inflammatory cytokines like IL‐10 and TGF‐beta, which suppress adaptive immune responses and promote tissue remodeling, angiogenesis, and tumor cell invasion." (PMID 39279550, 2024). "In summary, our current study demonstrates that vvDD-IL-9 treatment can deliver IL-9 into the tumor bed and elevate IL-10 expression." (PMID 38473379, 2024). "Eosinophil-derived cytokines IL-12 and IL-10 decrease metastasis by enhancing E-cadherin expression on tumour cells." (PMID 39471751, 2024). "Recent investigations had unveiled the capacity of CAFs to induce angiogenesis in endometrial malignancies via IL-10 secretion, thereby accelerating tumor advancement." (PMID 39138733, 2024).
tumor (continued). "The gut microbiota can produce butyrate, a short-chain fatty acid that has been shown to suppress the expression of PD-L1 and IL-10 in immune cells and demonstrate tumor growth inhibition potential in mouse models." (PMID 38812681, 2024). "Regulatory DCs within the TME can trigger regulatory T cell (Treg) activation and dampen cytotoxic T lymphocyte (CTL) recruitment to the tumor site by secreting suppressive cytokines like IL-10 and transforming growth factor-beta (TGF-β)." (PMID 38732975, 2024). "As they can inhibit anti-tumor immune effector responses in the TME by producing IL-10 and TGF-β, regulatory T cells (Tregs) are thought to support the survival of the TME." (PMID 38968580, 2024). "TAMs can secrete large amounts of the immunosuppressive cytokine IL-10, which prevents the tumor cell-killing activity of CD8+ T cells, Th1 cells, and NK cells and activates Treg recruitment." (PMID 39516356, 2024). "As observed in lymphocyte cultures, the cytokine IL-10 was differentially produced only in monocyte cultures with the empty vector and E5 transfected tumor cells, and IL-6 was highly produced in all experimental groups, especially when E7 was transfected." (PMID 38793599, 2024). "Among them, TNF‐α and IL‐2 are produced by Th1 cells and mediate anti‐tumour effects, while Th2 cells produce IL‐6 and IL‐10 and promote tumour growth by suppressing the immune system." (PMID 38451046, 2024). "IL-10 can suppress anti-tumor immune responses by inhibiting the activation of macrophages and dendritic cells, leading to reduced antigen presentation and T-cell activation." (PMID 39769247, 2024). "Decreased levels of IL-12 inhibit the killing activity of NK cells towards tumour cells and induce and recruit Tregs, while high levels of IL-10 interfere with DC maturation." (PMID 38475858, 2024). "IL-10 has been shown to play an important role in promoting tumor immune evasion by decreasing the antitumor immune response in the tumor microenvironment." (PMID 38957393, 2024). "In vitro experiments have demonstrated that specific blockade of tumor-secreted IL-10 and TGF-β can lead to the up-regulation of CD40, thereby enhancing the cytolytic activity of effector T cells against CCA cells." (PMID 39845973, 2024). "Second, TAMs secrete various immunosuppressive factors such as TGFβ, IL10 and NO to suppress the anti‐tumour immune response, thus promoting tumour cell proliferation." (PMID 38774995, 2024). "IL-35, another key cytokine, works in conjunction with IL-10 to induce an exhausted state in tumor-infiltrating lymphocytes and impairs the formation of T cell memory." (PMID 38500876, 2024). "Of note, negligible amounts of the cytokine IL-10, which is known to hinder anti-tumor response, were detected in all cultures that had been stimulated with IFN-DC." (PMID 39340087, 2024). "According to a ROC curve analysis, IL-10 spots after stimulation with tetanus toxoid were highly predictive of tumor burden (p = 0.005, AUC 0.90, sensitivity 100%, and specificity 78%)." (PMID 38473247, 2024). "These PD-L1 + TAMs were activated by tumour-derived interleukin-10 (IL-10), which can mediate the dysfunction of CD8+ T cells through PD-1/PD-L1 interaction." (PMID 39073672, 2024). "Tumor‐associated macrophages in the TME often adopt an M2‐like phenotype, promoting tumor growth, angiogenesis, and immunosuppression through cytokines like IL‐10 and TGF‐β." (PMID 39239068, 2024). "Tumor associated macrophage showed significant positive correlations with CCL2 (cor = 0.095, P = 3.41E−02*), CD68 (cor = 0.178, p = 6.79E−05*), and IL10 (cor = 0.219, p = 9.38E−07*)." (PMID 39030403, 2024). "Macrophages’ polarization is regulated by various microenvironmental signals from tumor cells, such as IL-4 and IL-10, which serve the same purpose." (PMID 38840908, 2024). "A variety of inflammatory mediators can induce MDSC expansion and recruitment to the TME, including tumor-derived IL-6, IL-8, IL-10, CSF-1, CCL2, CXCL2, PGE2, and TGF-β." (PMID 38254796, 2024).
tumor (continued). "Similar to the gene expression analysis of BM CD11b+ cells isolated from Egfl6 mice, CD11b+ cells isolated from 2F8c-Egfl6 tumors displayed higher IL10, Cxcl2, Clec5a, and Ceacam1 gene expression compared with tumor controls." (PMID 39312740, 2024). "M2d can suppress normal immune responses, enabling tumor cells to evade immune surveillance through the expression of IL-10, IDO, PD-1 ligands, and Siglec 15 ligands." (PMID 39796695, 2024). "IL-10, a pleiotropic cytokine, plays a crucial role in both inflammation and immunity within tumor microenvironment." (PMID 38279997, 2024). "TAMs suppress the function of CD8+ tumor-infiltrating lymphocytes (TILs) and exert immunosuppressive effects by secreting interleukin-10 (IL-10)." (PMID 39135069, 2024). "Nevertheless, when the tumor grows, the tumor cells repolarize to M2-type TAMs by a variety of pathways, including the production of cytokines including CSF-1, IL-4, and IL-10, lactate secretion, nutrient shortage, and hypoxia." (PMID 38185636, 2024). "Inflammatory cytokines, such as interleukin (IL)-1, IL-6, IL-10, tumor necrosis factor-α, macrophage migration inhibitory factor, and transforming growth factor-β, are involved in tumor initiation and progression." (PMID 38267838, 2024). "Preclinical studies have found that ascites IL-10 promotes tumor cell migration, and it is possible that IL-10 plays a major role in the immunosuppressed ascitic TME of OC." (PMID 39199610, 2024). "IL-10 expression in tumor cell lines transfected from IL-10 transgenic mice controls primary tumor growth and reduces the burden of metastasis." (PMID 38807592, 2024). "Treatment with MCP led to an increase in CD86 expression and TNF-α secretion, indicative of enhanced M1 polarization, while reducing CD206 and CD163 expression along with IL-10 secretion, thus supporting a shift towards a more anti-tumor immune response." (PMID 39593969, 2024). "IL-10 can suppress effective antitumor immune responses, facilitating tumor immune evasion by promoting chronic inflammation and a protumorigenic Th2 response." (PMID 39456897, 2024). "FLC slice cultures were treated with IgG control mAb, anti-PD-1 mAb, anti-IL-10 mAb, or anti-PD-1 plus anti-IL-10 mAbs for 6 days and tumor cell apoptosis was measured using cleaved caspase 3 (cC3) IHC." (PMID 38429349, 2024). "Taken together, these results illustrate that circLOC729852 inhibits the autophagy pathway in BLCA cells by suppressing miR‐769‐5p and upregulates IL‐10, thereby promoting tumour progression." (PMID 38506082, 2024). "To summarize, high circLOC729852 expression in BLCA promotes tumour progression and infiltration of M2 TAMs via the miR‐769‐5p/IL‐10 axis." (PMID 38506082, 2024). "That is because there exist a myriad of different cytokines in tumor tissues, such as interleukin (IL-10), transforming growth factor-β (TGF-β) and so on that can inhibit the function of effector T cells." (PMID 38428879, 2024). "Conversely, due to its immune-stimulating and anti-angiogenic properties, IL-10 is believed to have the ability to prevent or reduce tumor growth and distant metastasis." (PMID 38339076, 2024). "In this situation, TAMs accelerate tumor growth by activating the PPARδ to release the immunosuppressive cytokine IL-10." (PMID 38185636, 2024). "M2-like macrophages mediate the immune escape of tumor cells through PD-1 and are activated by interleukin (IL)-4, IL-10, IL-13, or colony-stimulating factor 1 (CSF-)." (PMID 39113885, 2024). "The qPCR analysis (n = 66) revealed an elevated expression of RUNX1 in tumor tissues (P < 0.0001), and the positive associations between RUNX1 mRNA and CD163 mRNA, Arg1 mRNA, CD68 mRNA, CD206 mRNA, IL-10 mRNA were observed (all P < 0.05)." (PMID 38419056, 2024).
tumor (continued). "Contrary to immunosuppressive aspects, IL-10 secreted by TAMs induces Tregs by activating Foxp3 expression, leading to tumor progression." (PMID 38279997, 2024). "The IL family, such as IL-6, IL-4, and IL-10, can polarize TAMs toward the M2 type with the pro-tumor effect and diminished antigen-presenting ability, which can decrease T-cell infiltration and promote the establishment of an immunosuppressive TME." (PMID 39497925, 2024). "For example, inflammatory cytokines, including CXCL5, CCL13, and IL10, produced by periostin-induced TAMs were found to create an immunosuppressive tumor microenvironment, leading to MF development." (PMID 39409988, 2024). "In tumor formation and metastasis, Tregs are the main source of IL-10, a kind of cytokine with durable and versatile anti-inflammatory effects." (PMID 39372416, 2024). "In tumors such as gastric cancer, TAM-produced IL-10 contributes to an immunosuppressive microenvironment that favors tumor growth." (PMID 38520006, 2024). "Further, NLGP supplementation to these tumor-conditioned mBMDCs boosted IL-12p35, with simultaneous repression of IL-10 levels, enhancing type 1 immune features back towards normal." (PMID 38649988, 2024). "Such flexibility afforded in the BM presumably by IL-10 can later support optimal adaptation of endothelial progenitors to the specific needs of tumor vascular bed." (PMID 38640116, 2024). "Tumor cells can secrete various immunosuppressive factors, including IL-10, TGF-β, and GM-CSF 34 cytokines." (PMID 38887597, 2024). "The combination treatment, Egfl6 NAb and a-PD-L1, was associated with (a) a reduced number of intratumoral PMN-MDSCs and TAMs, (b) reduced PMN-MDSC and TAM secretion of IL-10 and Cxcl2, and (c) increased tumor infiltration of antitumor MHC-II+ macrophages." (PMID 39312740, 2024). "MDSCs can indirectly enhance their own anti-tumor immune effects by producing iNOS, IL-10, TGF-β, and CD274, thereby promoting Treg development." (PMID 39227970, 2024). "On the other hand, M2 macrophages express high levels of VEGF, IL-10, IL-1β, and matrix metalloproteinases (MMPs), which contribute to chemoresistance, tumor angiogenesis and metastasis." (PMID 39003350, 2024). "M2 macrophages, on the other hand, secrete anti-inflammatory cytokines, such as IL10 and TGFβ, display immunosuppressive behaviours, and deplete nutrients for T cell response against the tumour." (PMID 38339377, 2024). "ZTA can also promote the secretion of IL-10, which plays an essential role in tumor immune evasion and tumor-promoting immunity." (PMID 38206974, 2024). "Within the chaotic realm of the tumor microenvironment, M2 macrophages play a significant role, secreting cytokines such as interleukin-10 (IL-10) and transforming growth factor-β (TGF-β)." (PMID 39081317, 2024). "Exosomal microRNA-214, in terms of its mechanism, suppresses the expression of phosphatase and tensin homolog (PTEN) in T cells and induces regulatory T cells (Tregs) to secrete IL-10, which ultimately leads to the promotion of tumor growth." (PMID 38553754, 2024). "Tumors can transform DCs into FOXP3+ Tregs, and DCs can also secrete IL-10 to induce the transformation of T cells into Tregs, thus revealing that DCs can promote tumor development." (PMID 39263534, 2024). "The administration of PBMCs from GC patients enhanced tumor cell growth, whereas butyrate inhibited tumor cell growth by inhibiting the expression of immunosuppressive markers, including PD-L1 and IL-10." (PMID 38197259, 2024). "In mice receiving only carbo/pax chemotherapy, strong positive correlations with tumor burden were found for IL-7 (r = 0.8734, p = 0.0230), IL-10 (r = 0.8912, p = 0.0171), and CXCL10 (IP-10) (r = 0.9433, p = 0.0047)." (PMID 39623404, 2024). "M2 macrophages secrete various cytokines such as TGF-β and IL-10, which can promote tumor cell proliferation and inhibit the anti-tumor activity of T cells and NK cells." (PMID 39767730, 2024).
tumor (continued). "There is increasing evidence that IL-10 can induce anti-tumor effects in an immune-dependent manner." (PMID 39796154, 2024). "IL-10-Fc or BF10 monotherapy effectively suppressed tumor growth and possessed survival benefits as expected." (PMID 37586318, 2023). "In contrast, regulatory B cells increase tumor activity through immunosuppressive factors, such as IL-10 and TGF-β14,15." (PMID 37828063, 2023). "This last type of microenvironment is common in tumors, and it is characterized by the presence of IL-10 and IL-6, which favors tumor proliferation and metastasis." (PMID 37283734, 2023). "When accumulated in the tumor microenvironment, MDSCs produce and release IL-10, TGF-β, and other molecules that promote neo-angiogenesis and exert immunosuppressive activity, facilitating tumor growth, survival, and progression." (PMID 38136673, 2023). "In TAM, in colon cancer cells, PKN2-inducible DUSP6 leads to the suppression of tumor-associated M2 macrophage polarization and tumor growth, through the inhibition of the ERK1/2, IL-4, and IL-10 cascade." (PMID 38139370, 2023). "MM and tumor microenvironment cells secrete IL-10, TGF-β, immunosuppressive ectoenzymes and other soluble factors, which potentially modulate the cytotoxic activity of CD8+ cells." (PMID 38213954, 2023). "The increase of IL10 at later timepoints was observed in both treated and untreated cohorts and is likely an immune evasion mechanism deployed by the 4T1 tumor." (PMID 36968140, 2023). "In the present study, we discovered that peroxisome proliferator-activated receptor delta (PPARδ) is highly expressed in IL-10-producing Bregs and serves as a key regulator controlling their development and function in tumor-bearing mice and cancer patients." (PMID 37291146, 2023). "TAMs remodel the TME by releasing the inhibitory cytokines, including TGF-β and IL-10, and expressing immune checkpoint ligands to inhibit infiltration and anti-tumor activity of other immune cells, especially cytotoxic T cells." (PMID 36761751, 2023). "Tregs also affect tumor-infiltrating pDCs and secrete the suppressive cytokines IL-10 and TGF-β, which alter the pDC phenotype, inhibit immune activation through the classical pathway, impair IFN-α production by pDCs, and enhance tumor immunosuppression." (PMID 37817484, 2023). "It has been shown that the cytokines released by TH2 cells, including IL-17, IL-13, IL-10, IL-5, and IL-4, inhibit tumor growth." (PMID 37892995, 2023). "Since STAT3 signaling is primarily responsible for the transcription of IL-10 in GAMs, overactive pSTAT3 expression has been linked to both a worse survival rate for GBM patients and an increase in tumor grade." (PMID 37237548, 2023). "Predominantly anti‐inflammatory markers, such as CD206, IL‐10, IL‐8, CCL8, and CCL22 are known to be associated with advanced tumor stage and poor survival." (PMID 38037545, 2023). "Lactate secreted by CC cells mediates crosstalk between tumor cells and macrophages, which promotes the secretion of IL-1, IL-10, and IL-6, and upregulates the expression of hypoxia-induced factor-1, further promoting a suppressive phenotype." (PMID 37234990, 2023). "Tumor cells are known to secrete immunosuppressive factors such as TGFβ, IL-10, adenosine, prostaglandine E2 (PGE2), idoleamine 2,3-dioxygenase (IDO) and lactate leading to tumor cell evasion." (PMID 37691935, 2023). "There are three types of M2 macrophages (M2a, M2b, and M2c), which secrete common immunosuppressive cytokines (TGF-β and IL-10) and chemokines to support tumor growth." (PMID 37275901, 2023). "Macrophages have been mainly reported as tumor-promoting cells in many types of tumors, through their ability to produce immunosuppressive cytokines, such as interleukin (IL)-10 and IL-1Ra." (PMID 37370706, 2023).